KLF4 (KLF transcription factor 4)
Diseases named in the same sentence as KLF4 in open-access papers (continued):
Sharing a sentence is not in itself a finding about the gene and the disease.
breast cancer (continued). "Furthermore, the miR-29 family members directly target Krüppel-like factor 4 (KLF4), a transcription factor required for the maintenance of breast cancer stem cells, and down-regulation of miR-29 family members results in increased stem-like properties in vitro and in vivo." (PMID 25886595, 2015). "In this study, we found that both KLF4 and a downstream effector, microRNA-206 (miR-206), are selectively enriched in the MaCSC fractions of cultured human TNBC cell lines, as well as in the aldehyde dehydrogenase-high MaCSC sub-population of cells derived from xenografted human mammary carcinomas." (PMID 26053033, 2015). "We have identified the zinc-finger transcription factor Kruppel-like factor 4 (Klf4) among the transcription factors that are significantly downregulated in their expression during epithelial-mesenchymal transition (EMT) in mammary epithelial cells and in breast cancer cells." (PMID 23451207, 2013). "Moreover, high expression level of KLF4 occurred preferentially in the tumor cells and not the adjacent non-tumor cells in mammary carcinoma (P < 0.001)." (PMID 21978458, 2011). "Moreover, we demonstrated that overexpression of KLF4 can increase PTX-induced inhibition of cell growth and promoted apoptosis of MCF-7 and T47D cells, which indicates that restoring KLF4 expression of breast cancer cells could be an effective way to overcome PTX resistance." (PMID 34150611, 2021). "However, the effect of KLF4 in PTX sensitivity of breast cancer cells has not been reported." (PMID 34150611, 2021). "Moreover, we observed significant upregulation of several crucial stem cell factors such as Myc, Sox9 and BMI1 in response to elevated expression of KLF4 but not KLF4-3K, which suggests a critical role of KLF4 in the maintenance of self-renewal for breast cancer stem cell." (PMID 26420673, 2015). "Of note, Jurkat cell-derived CM, which was generated from the overexpression of c-Myc/Oct4 as well as Sox2/Klf4 did not induce detectable changes in MTT-based viability and transwell invasion in 4T1.2 mammary tumor cells." (PMID 35547745, 2022). "Overexpression of NFI-C and NFI-X resulted in a statistically significant increase in KLF4 and E-cadherin transcriptional activity in MCF7 breast cancer cells, while NFI-A and NFI-B overexpression did not." (PMID 25879941, 2015). "The expression of EMT associated marker genes in ovarian cancer cells are similar to what we observed in MCF7 breast cancer cells, although the endogenous expression of vimentin in MCF7 was not detectable in KLF4-overexpressing or control cells." (PMID 25137052, 2014). "Additionally, we found that breast cancer cells that overexpress MEG8 have decreased the expression levels of some stem cell markers such as BMI1, SOX9 and KLF4 and in some cases also NANOG or SOX2, but not OCT4." (PMID 39706842, 2024). "Besides, Sox2 and Klf4-overexpressing MSCs-derived CM also did not induce detectable changes in MTT-based viability and scratch-based migration in 4T1.2 mammary tumor cells." (PMID 35547745, 2022). "Indeed, OPG upregulation promoted the pro-metastatic processes EMT and stemness in the non-carcinogenic (MCF-10A) and luminal breast cancer (T-47D, MCF-7) cells, through upregulating the mesenchymal (N-cadherin, SNAIL and ZEB1) and stemness (CD44, ALDH1, Nanog, Klf-4 and Sox2) markers." (PMID 39181873, 2024).
atherosclerosis (113 papers, 2013 to 2026). A disease characterized by the build-up of fatty material and calcium deposition in the arterial wall resulting in partial or complete occlusion of the arterial lumen. "We previously established that increased intracellular cholesterol activates PERK/ATF4/KLF4 signaling and is responsible for a component of atherosclerosis-associated phenotypic modulation of SMCs." (PMID 37937642, 2023). "In an earlier study, KLF4-dependent effects on the phenotype transition in vascular smooth muscle cells were pathogenic, and knockout of KLF-4 in an atherosclerosis mouse model diminished the size of the lesions." (PMID 35884997, 2022). "During atherosclerosis, deficiency of KLF4 showed reduced lesion size, while OCT4 deficiency showed an increase in lesion size." (PMID 34470477, 2021). "For instance, both hemizygous Klf2 germline deletion or endothelial-specific Klf4 loss sensitized atheroprone apolipoprotein E–deficient (ApoE−/−) mice to high fat diet-induced atherosclerosis." (PMID 34299213, 2021). "In atherosclerosis, Alencar et al33 identified a reduction in lesion size and increased plaque stability in mice with a vSMC-specific conditional deficiency of KLF4." (PMID 34470477, 2021). "KLF4 acts as a novel important regulator for the macrophage behaviors implicated in the chronic inflammatory diseases, especially atherosclerosis." (PMID 32065217, 2020). "Moreover, scRNA-seq data from WT and Klf4-knockout SMC lineage mice revealed that key female drivers of SMC were associated with Klf4, suggesting that sex differences in atherosclerosis are associated with phenotypic transformation of plaque SMCs." (PMID 36267275, 2022). "Moreover, loss of myeloid KLF4 is associated with augmented atherosclerosis, and macrophages deficient in KLF4 display increase inflammation in response to oxidized phospholipids." (PMID 29459900, 2018). "Further studies are needed to verify our hypothesis that activation of AMPK/KLF4 signaling by loss of Elovl6 is protective against atherosclerosis by using double knockout mice of Elovl6 and apoE." (PMID 27881420, 2016). "The enhanced synthetic phenotype driven by the SUMOylation-deficient mutant highlights the importance of SENP3-dependent deSUMOylation in fully activating KLF4-mediated phenotypic switching during atherosclerosis." (PMID 41307849, 2025). "For example, both KLF2 and KLF4 members can protect ECs, which exerts a beneficial effect on atherosclerosis." (PMID 41373858, 2025). "This KLF4–Ch25h/LXR homeostasis axis exhibits anti‐inflammatory properties and reduces susceptibility to atherosclerosis by inhibiting inflammatory vesicle activity in endothelial cells (ECs) and facilitating a shift from the M1 to M2 phenotype in macrophages." (PMID 41020041, 2025). "While Piezo1 deletion ameliorates atherosclerosis, it also exerts physiological anti-inflammatory effects via KLF4." (PMID 41372156, 2025). "S-flow activates KLF2 and KLF4, transcription factors critical for suppressing atherosclerosis by modulating endothelial nitric oxide synthase (eNOS)-associated pathways, including cGMP-PKG, cAMP, and insulin signaling." (PMID 41373858, 2025). "Under specific conditions and mechanisms such as SENP1-mediated de-SUMOylation of KLF4, KLF4 shifts its function to enhance MØ M1 polarization and promote atherosclerosis (represented by a green “+” icon)." (PMID 41155497, 2025). "Currently, Klf4 has been proposed as a biomarker for several systemic conditions, such as atherosclerosis and lung cancer." (PMID 40076622, 2025). "Similar to KLF2, KLF4 exerts protective effects in atherosclerosis through EC protection, inflammation modulation, and PCD regulation." (PMID 41373858, 2025). "Collectively, these mechanisms—distinct yet complementary to those of KLF2—highlight the multifaceted protective role of KLF4 in atherosclerosis." (PMID 41373858, 2025).
atherosclerosis (continued). "In fact, it is noteworthy that the promoting or inhibitory effects of KLF4 in atherosclerosis primarily depend on the specific target cells." (PMID 39062998, 2024). "Our research illustrates that quercetin inhibits the KLF4-mediated phenotypic switch of VSMCs to macrophage-like cells and reduces atherosclerosis by suppressing the JAK2/STAT3 pathway." (PMID 39062998, 2024). "The presence of KLF4, another crucial member, suppresses the progression of atherosclerosis (AS) and pulmonary hypertension by attenuating the formation of VSMCs-derived foam cells, ameliorating endothelial dysfunction, and inducing vasodilatory effects." (PMID 38745757, 2024). "During atherosclerosis, KLF4 maintains normal vascular wall shear stress and vasopermeability and prevents the secretory phenotype switching from the contraction phenotype of smooth muscle cells and fibroblast inflammation." (PMID 38728249, 2024). "Recent research has revealed that C1q/tumor necrosis factor-related protein 9 relies on the AMPKα pathway to reduce KLF4 expression, inhibit hyperglycemia-induced endothelial senescence, and attenuate atherosclerosis." (PMID 39062998, 2024). "Recent research has shown that the transcription factor homeobox A1 participates in atherosclerosis progression by activating KLF4 expression, thereby promoting the phenotypic switch of VSMCs to macrophage-like cells." (PMID 39062998, 2024). "Atherosclerosis and decreased levels of KLF-4 in the aorta are typical symptomatology of diabetes, as seen in mice models, which ultimately leads to coronary atherosclerotic heart disease, stroke, and PAD." (PMID 36836777, 2023). "DNMT1 also hypermethylates the promoter of atheroprotective Krüppel-like factor 4 (KLF4), downregulating its expression and promoting M1 macrophage inflammation and atherosclerosis." (PMID 37947606, 2023). "EVs aggravate not only endothelial inflammation but also atherosclerosis by delivering miR-1, which induces the inhibition of Kruppel like factor 4 (KLF4) and activation of the NF-κB pathway." (PMID 37534206, 2023). "The protective effects of KLF2 and KLF4 in atherosclerosis make them an attractive target for the development of new treatments for cardiovascular diseases." (PMID 36984888, 2023). "Contrary to the previous findings in SMC, KLF4 depletion in endothelial and myeloid cells drives atherosclerosis progression." (PMID 37991018, 2023). "Depletion of stemness transcription factor KLF4 specifically in AdvSca1-SM cells alters their differentiation trajectory in atherosclerosis." (PMID 37991018, 2023). "The large family of KLFs in humans includes 18 members, among which KLF2 and KLF4 are at the crossroads between endothelial cell mechanobiology and immunometabolism, which play important roles in both the normal vascular wall and atherosclerosis." (PMID 36984888, 2023). "On the other hand, cholesterol-loaded smooth muscle cells can induce KLF4 expression and transform smooth muscle cells into a foam cell phenotype, which is a key feature of atherosclerosis." (PMID 36984888, 2023). "Our study also identified specific atherosclerosis-related transcription factors KLF4, KLF11 and BCLAF1 upstream from FURIN, PCSK6 or PCSK7." (PMID 36188622, 2022). "Previous studies have revealed that KLF2 and KLF4 have an anti-inflammation function, which thereby protects aortic vessels from atherosclerosis." (PMID 35883633, 2022). "It has been reported that Tan IIA downregulates mmu-miR-375 to increase the KLF4 protein expression and ameliorate atherosclerosis in ApoE knockout mice." (PMID 35832651, 2022). "Formononetin, an AM component, alleviated atherosclerosis in ApoE-/- mice by regulating the interaction between krüppel-like factor 4 (KLF4) and steroid receptor RNA activator 1 (SRA)." (PMID 35267929, 2022).
atherosclerosis (continued). "Laminar blood flow was found to induce KLF2 and KLF4 expression in the vascular endothelium, whereas KLF2 and KLF4 expression is reduced in areas of impaired blood flow as well as in areas prone to atherosclerosis." (PMID 36077168, 2022). "Conversely, expression of an EC-specific Klf4 transgene protected ApoE−/− mice from high fat diet-induced atherosclerosis." (PMID 34299213, 2021). "In VSMCs, increased expression of miR-92a, induced by PDGF-BB during the formation of atherosclerosis plaque in mice, promotes cell proliferation and migration via targeting KLF4." (PMID 33738288, 2021). "In atherosclerosis, specific Klf4 deletion in VSMCs prevents lesion development by diminishing VSMC transition to mesenchymatic and foam cell formation, while Oct4 deficiency in VSMCs yields opposing gene expression and large lesions with thin fibrous caps." (PMID 34829747, 2021). "In conclusion, our results demonstrated a novel role of DJ‐1 in inhibiting the progression of atherosclerosis and unveiled a new theory underlying the control of phenotypic switching of VSMCs via ERK/KLF4." (PMID 33501750, 2021). "As a zinc finger domain-containing transcription factor, KLF4 involves in atherosclerosis development 27,65." (PMID 31938053, 2020). "Others have shown that SMC-specific depletion of KLF4 attenuates experimental atherosclerosis lesion formation and abdominal aortic aneurysm formation." (PMID 33119549, 2020). "The protective roles of KLF2 and KLF4 have been demonstrated in experimental models of atherosclerosis (ApoE-deficient and LDL receptor-deficient mice), where deficiency of KLF2 and KLF4 accelerates the process." (PMID 31354915, 2019). "Klf4 has been identified as a critical molecule involved in the pathogenesis of atherosclerosis in macrophages and ECs." (PMID 29324844, 2018). "Exposure of ECs to pro-inflammatory cytokines or shear stress reduces their expression of Klf4, deletion of endothelial Klf4 augments atherosclerosis, and transgenic EC-Klf4 reduces atherosclerosis." (PMID 29324844, 2018). "Conversely, endothelial-driven overexpression of Klf4 is protective against atherosclerosis and thrombosis." (PMID 29459900, 2018). "Previous study reports that miR-103 promotes endothelial maladaptation and atherosclerosis by mediating suppression of KLF4." (PMID 28445396, 2017). "Previous reports showed that miR-103 induced the endothelial dysfunction and atherosclerosis by suppressing KLF4 expression." (PMID 28938633, 2017). "Inhibiting the interaction between miR-103 and KLF4 reduces atherosclerosis, lesional macrophage accumulation and endothelial CXCL1 expression." (PMID 26837267, 2016). "Overall, our study suggests that Dicer promotes endothelial maladaptation and atherosclerosis in part by miR-103-mediated suppression of KLF4." (PMID 26837267, 2016). "Here the authors show that endothelial Dicer promotes atherosclerosis by increasing miR-103 levels leading to suppression of the anti-inflammatory transcription factor KLF4, thus suggesting a novel approach to treat this disease." (PMID 26837267, 2016). "Considering a variety of target genes of Nkx2‐5 involved in atherosclerosis, how much of a difference will KLF4 make?" (PMID 27993833, 2016). "Blocking the interaction between miR-103 and KLF4 in arteries reduced atherosclerosis, lesional macrophage accumulation and CXCL1 expression, similar as the deletion of Dicer in ECs." (PMID 26837267, 2016). "Inhibition of the miR-103-KLF4 interaction reduced atherosclerosis, lesional macrophage accumulation and endothelial CXCL1 expression in the arteries of Apoe−/− mice, indicating a proinflammatory and proatherogenic role of miR-103 by targeting KLF4." (PMID 26837267, 2016). "POVPC is concentrated within atherosclerotic lesions and contributes to the pathogenesis of atherosclerosis by inducing profound suppression of vascular smooth muscle cell differentiation marker genes via a transcription factor KLF4 (L5)." (PMID 24564975, 2013).
atherosclerosis (continued). "Thus, under atherogenic conditions, upregulation of SENP3 represents a critical mechanism that amplifies KLF4 signaling by preventing its degradation and fine-tuning its activity, thereby driving VSMCs plasticity and atherosclerosis progression." (PMID 41307849, 2025). "Notably, disturbed flow patterns, which are found in vascular areas predisposed to atherosclerosis, significantly reduce the endothelial expression of KLF2 and KLF4, resulting in changes in the transcriptome that exacerbate inflammation and thrombosis." (PMID 40362576, 2025). "Both polarizing events depend on the KLF4-galectin-3 axis, implying that VSMC-specific targeting of KLF4/galectin-3 function could be beneficial as a therapeutic strategy in the treatment of atherosclerosis." (PMID 41155497, 2025). "In contrast, KLF4 is a key driver of vSMC dedifferentiation during atherosclerosis." (PMID 40172727, 2025). "As the pathogenesis of periodontitis is indicated by its multiple stages, it is interesting that monitoring Klf4 expression could provide insights into the severity and stage of atherosclerosis." (PMID 40076622, 2025). "Fosb and Jun have specific roles in mediating cellular and arterial contractility, Atf3 is a CAD GWAS gene and has recently been identified to have vascular protective effect in atherosclerosis, and Klf4 has critical roles in mediating SMC phenotypic modulation and promotes atherosclerosis." (PMID 40931195, 2025). "Although no studies have directly examined whether Minocycline regulates p27KIP1 through the KLF4 pathway, the roles of KLF4 and Minocycline in atherosclerosis overlap." (PMID 41373858, 2025). "Consequently, targeting the KLF4-mediated phenotypic modulation of VSMCs represents a promising therapeutic strategy for atherosclerosis." (PMID 39062998, 2024). "Krüppel-like factor 4 (KLF4), functioning as a transcription factor, plays a critical role in regulating the phenotypic switch of vascular smooth muscle cells (VSMCs) to macrophage-like cells during the pathogenesis of atherosclerosis." (PMID 39062998, 2024). "Nevertheless, whether and how KLF4 regulates ECs’ inflammatory factors release in SASP in atherosclerosis remains unknown." (PMID 38728249, 2024). "First, due to enhanced expression of PU.1, KLF4, MafB, and LXRα, these cells acquired antiinflammatory properties, including the increased secretion of IL-10, IL-1RA, and IL-5, aiding to resolve inflammation and protect against atherosclerosis." (PMID 39531328, 2024). "Our findings provide, for the first time, novel evidence that quercetin suppresses the phenotypic switch of VSMCs to macrophage-like cells by inhibiting the JAK2/STAT3 pathway and reducing KLF4 expression, thereby preventing foam cell formation and attenuating atherosclerosis." (PMID 39062998, 2024). "Therefore, further investigation is needed to determine the precise role of quercetin in preventing atherosclerosis through its interaction with KLF4." (PMID 39062998, 2024). "Consequently, KLF4 confers cardioprotective effects that attenuate atherosclerosis/atherothrombosis and raise the threshold for autoimmune and other inflammatory diseases." (PMID 38406578, 2023). "The role of KLF4 in atherosclerosis is complex and cell-type-dependent." (PMID 36984888, 2023). "Thus, KLF2 and KLF4 play crucial roles in the molecular mechanisms of atherosclerosis, regulating multiple pathways involved in endothelial cell function and other vascular wall and blood flow cells, as well as in inflammation and lipid metabolism." (PMID 36984888, 2023). "Loss of KLF4 may lead to the downregulation of OCT4, which seems to be contrary to the anti-atherosclerosis effect of OCT4." (PMID 36604627, 2023). "KLF4 is known to regulate tissue homeostasis and repair in the endothelial cells by promoting vascular integrity and regulating smooth muscle cell phenotype transition in atherosclerosis." (PMID 37615937, 2023).